NRAS (NRAS proto-oncogene, GTPase)
Diseases named in the same sentence as NRAS in open-access papers (continued):
Sharing a sentence is not in itself a finding about the gene and the disease.
neuroblastoma (47 papers, 2012 to 2025). Neuroblastoma (NB) is the most common solid, extracranial childhood tumor. "Next-generation DNA sequencing (NGS) of the primary tumor, performed using the Ion AmpliSeq Cancer Hotspot Panel v2 (Thermo Fisher Scientific, San Francisco, CA, USA), identified a neuroblastoma RAS viral (v-ras) oncogene homologue (NRAS) mutation (p.G12S)." (PMID 40589558, 2025). "Pathological findings confirmed R0 resection, and genetic analysis identified a neuroblastoma RAS viral (v-ras) oncogene homologue (NRAS) mutation (p.G12S)." (PMID 40589558, 2025). "Genetic analysis of peripheral blood mononuclear cells showed that the patient was positive for neuroblastoma RAS (NRAS) mutation." (PMID 35601422, 2022). "In line with our in vitro data, we detected de novo NF1 and NRAS or HRAS mutations in neuroblastomas from patients treated with the ALK inhibitors, ceritinib or lorlatinib, at resistance development." (PMID 35689207, 2022). "Genetic analysis of peripheral blood mononuclear cells showed that the patient was positive for neuroblastoma RAS (NRAS) mutation [Codon 12, 13 mutation-positive c.35G>A (amino acid change p.G12D)]." (PMID 35601422, 2022). "NRAS, a GTPase encoded by NRAS gene, originally identified in neuroblastoma cell lines, was considered as the third member of RAS family." (PMID 33193737, 2020). "Half of the patients with advanced CRC harbor a KRAS or a neuroblastoma N-Ras (NRAS) tumor gene mutation." (PMID 33256240, 2020). "As well as MYCN amplification, activating point mutations of ALK and NRAS are associated with high-risk and relapsing neuroblastoma." (PMID 28602975, 2017). "Taken together, these data show that NRAS Q61K mutations in neuroblastoma result in hyperactivation of the RAS/RAF/MEK/ERK pathway and sensitize to MEK inhibitors." (PMID 26821351, 2016). "One additional NRAS-mutated case was identified in additional 500 patients who are of low-, intermediate- and high-risk neuroblastoma." (PMID 26821351, 2016). "Analysis of the NRAS gene in our panel of neuroblastoma cell lines revealed two NRAS mutations at position Q61K in the CHP-212 and SK-N-AS cell line, which was also the most common mutation in the primary tumors." (PMID 26821351, 2016). "A study which reviewed the genetic aberrations of 240 stage IV neuroblastoma patients reported NRAS mutations in 0.83% of the studied tumors." (PMID 25277205, 2014). "Sequencing analysis of MM patient samples has shown that the Kirsten RAS (KRAS) oncogene is the most commonly mutated gene (36%) in the disease, followed by the neuroblastoma RAS (NRAS) (20%), with frequent co-existence of one or more variants in both KRAS and NRAS cancer-driver genes." (PMID 36523963, 2022). "In neuroblastoma, NRAS status was found to be associated with the sensitivity to SHP2 inhibitors." (PMID 33193737, 2020). "NRAS und ALK mutations in selected neuroblastoma cell lines." (PMID 26821351, 2016). "Especially Everolimus as currently available drug could be an alternative option for NRAS mutated neuroblastoma patients being refractory to other treatments." (PMID 26821351, 2016). "Additionally, several genetic alterations including MEG3 polymorphisms, ERCC1/XPF, and NRAS were associated with the occurrence of neuroblastoma and might serve as important diagnosis biomarkers in the future." (PMID 32695501, 2020). "The KRAS gene belongs to the RAS oncogene family, which possesses two distinct human isoforms: neuroblastoma and Harvey rat sarcoma viral oncogene (NRAS and HRAS)." (PMID 40075634, 2025). "The last gene, NRAS, is localized on the short arm of chromosome 1 (1p22–1p32) and is identified in human neuroblastoma." (PMID 40075634, 2025).
neuroblastoma (continued). "NRAS, neuroblastoma-RAS, is one of the three RAS genes involved in the crossroads between cell surface receptors and internal cellular processes, leading to cell proliferation, differentiation, and apoptosis." (PMID 40447784, 2025). "A similar trend was observed in NRAS-mutant neuroblastoma cells, SH-EP, upon induction of Mb24 expression." (PMID 39379700, 2024). "Here, the authors identify loss of miR-1304-5p as a driver of ALK inhibitor resistance via regulation of NRAS, and therapeutically target this axis with the addition of a farnesyltransferase inhibitor in preclinical models of neuroblastoma." (PMID 38653965, 2024). "The three most widely studied RAS genes in humans are HRAS, KRAS, and NRAS, named after the Harvey Rat sarcoma virus, Kirsten Rat sarcoma virus, and NRAS, for its initial identification in neuroblastoma cells." (PMID 37529712, 2023). "Four neuroblastoma cell lines were included based on the presence of the most common mutations affecting the RAS-MAPK pathway, RAS (KRAS in SJNB8 and NRAS in SKNAS), NF1 (SKNBE) and ALK (KCNR)." (PMID 36895472, 2023). "For example, in each neuroblastoma tumour sample, a mutation was present in only one out of five putative driver genes—ALK, ATRX, PTPN11, MYCN or NRAS." (PMID 34434669, 2021). "We observed dose-dependent growth inhibition of the NRAS mutant neuroblastoma cell lines CHP-212 and SK-N-AS treated with MEK inhibitors AZD6244, MEK162 and PD0301925." (PMID 26821351, 2016). "More importantly, Everolimus induced apoptosis significantly in NRAS mutant neuroblastoma CHP-212 cells." (PMID 26821351, 2016). "In conclusion, we show that mutant NRAS neuroblastoma can be targeted by single MEK and mTOR inhibitors or their combinations." (PMID 26821351, 2016). "In our study, we demonstrate that inhibition of the mTOR pathway by Everolimus alone is sufficient to block cell growth in NRAS mutant neuroblastoma cells compared to wild type cells." (PMID 26821351, 2016). "This indicated that IC50 values for both NRAS mutant neuroblastoma cell lines were at a sensitive level for plasma concentrations of Everolimus." (PMID 26821351, 2016). "In summary, inhibition of mTOR complex alone by Everolimus reduced cell growth and induced apoptosis in NRAS mutant neuroblastoma." (PMID 26821351, 2016). "Encouraged by these findings, we aimed to investigate how the combination of mTOR inhibitors and MEK inhibitors would affect cell growth of NRAS mutant neuroblastoma cell lines." (PMID 26821351, 2016). "Two NRAS and one HRAS mutation were described in two of the genomic landscape studies of neuroblastoma." (PMID 26821351, 2016). "Strikingly, inhibition of the mTOR pathway alone resulted in a strong blockage of cell growth in NRAS mutant neuroblastoma cancer cell lines compared to wild-type." (PMID 26821351, 2016). "NRAS wild-type neuroblastoma cell lines SH-SY5Y, CHP-134 and NGP were refractory to MEK inhibitors even at high micromolar concentrations." (PMID 26821351, 2016). "Another RAS family member was identified from a human neuroblastoma cell line, neuroblastoma RAS (NRAS), and is also mutated in various human cancers." (PMID 22928112, 2012). "It was shown that inhibition of PTPN11 might be an effective strategy to overcome NRAS-dependent resistance in neuroblastoma or KIT-induced myeloproliferative diseases." (PMID 37384296, 2023). "This is an intriguing finding since Everolimus is currently indicated and available for the treatment of renal cell cancer and pancreatic neuroendocrine tumors and could be of value for carefully selected patients with NRAS mutant neuroblastomas." (PMID 26821351, 2016).
neuroblastoma (continued). "Likewise, sgRNAs for NRAS and MAP2K1 (MEK1), a downstream kinase of mutant NRAS, were identified among the top hits in the NRAS-mutant neuroblastoma cell line CHP-212." (PMID 27613601, 2016). "Interestingly, combination of MEK and mTOR inhibitors is synergistic in NRAS mutant neuroblastoma cell lines which were observed for both cell lines." (PMID 26821351, 2016). "Here, we investigated the druggability of NRAS in neuroblastoma." (PMID 26821351, 2016). "However, few inhibitors for the potential treatment for NRAS mutant neuroblastoma have been investigated so far." (PMID 26821351, 2016). "Taken together, our results show that NRAS mutant neuroblastoma can be targeted by clinically available Everolimus alone or in combination with MEK inhibitors which could impact future clinical studies." (PMID 26821351, 2016). "We found that Everolimus alone induced apoptosis in NRAS mutant neuroblastoma." (PMID 26821351, 2016). "We conclude that NRAS activity is required for viability of NRAS mutant neuroblastoma." (PMID 26821351, 2016). "The most frequently harbored alterations of specific genes in neuroblastoma include heritable mutations in the ALK and PHOX2B observed in familial neuroblastoma, chromatin remodeling genes like ATRX, ARID1A and ARID1B and other important genes like PTPN11, MYCN, and NRAS." (PMID 37274289, 2023). "NRAS, a proto-oncogene of the RAS family, was initially discovered in neuroblastoma and drives ferroptosis through lipid metabolism regulation, emerging as a novel prognostic marker." (PMID 40108662, 2025). "The KRAS gene is a member of the rat sarcoma viral oncogene family (RAS), which includes two other isoforms in humans: the Harvey and neuroblastoma rat sarcoma viral oncogenes (HRAS, NRAS)." (PMID 34776511, 2021). "The Ras family proteins HRAS and NRAS, comprised in the term “prenylation”, were significantly upregulated in ALT-positive neuroblastomas." (PMID 33627664, 2021). "Targeting of the PI3K/AKT pathway seemed not to have some effect on NRAS mutant neuroblastoma cells." (PMID 26821351, 2016). "In this in-vitro study, we show that MEK inhibitors AZD6244, MEK162 and PD0325901 block cell growth in NRAS mutant neuroblastoma cell lines but not in NRAS wild-type cell lines." (PMID 26821351, 2016). "Our data suggest that the PI3K/AKT pathway is, at least in these model systems, not relevant for survival and cell growth of NRAS mutant neuroblastoma cells." (PMID 26821351, 2016). "More importantly, Everolimus alone was sufficient to induce apoptosis in NRAS mutant neuroblastoma cell lines but not in wild-type cell lines." (PMID 26821351, 2016). "These lines represent MYCN-amplified, NRAS and ALK mutant neuroblastoma subtypes respectively." (PMID 26517508, 2015). "Additionally, we recently demonstrated an unexpected role for the leucine G-protein coupled receptor (LGR5) as a critical upstream regulator of MEK-ERK signaling and cell survival of different neuroblastoma genetic subtypes, including ALK and NRAS mutant lines." (PMID 28602975, 2017). "However, we could not observe a synergism of AKT inhibitor MK2206 and MEK inhibitors AZD6244 and MEK162 in NRAS mutant neuroblastoma cell lines (data not shown)." (PMID 26821351, 2016). "Regarding the NRAS mutant neuroblastoma, this might implicate that phosphorylation of AKT is independent of upstream PI3K activity in these cell lines and that mutant NRAS does not signal via the PI3K/AKT axis." (PMID 26821351, 2016). "Interestingly, the NRAS Q61K neuroblastoma cell lines SK-N-AS and CHP-212 showed a significant decrease in cell growth after siRNA mediated NRAS knock-down, compared to cells transfected with non-targeting control siRNA." (PMID 26821351, 2016).
pancreatic cancer (40 papers, 2012 to 2026). "The same C118S mutation engineered into HRAS and NRAS was previously shown to reduce the tumor growth of the KRAS mutation-positive human pancreatic cancer cell line CFPac-1." (PMID 25902334, 2015). "The RAS protein family—KRAS, NRAS, and HRAS—consists of small GTPases, with KRAS mutations detected in 86–91% of pancreatic cancer cases." (PMID 39770538, 2024). "RAS (KRAS, NRAS, and HRAS) is the most frequently mutated gene family in cancers, especially lung, colorectal, and pancreatic cancers." (PMID 36817861, 2023). "In the case of PAAD, where more than 94% Pancreatic cancer patients harboring KRAS mutations, there is also a strong association between KRAS mutation status and increased level of expression of NRAS." (PMID 30517129, 2018). "Solid tumors such as colorectal and pancreatic cancers showed frequent KRAS mutations, whereas some hematologic cancers such as acute lymphoblastic leukemia predominately showed NRAS mutations." (PMID 27634910, 2016). "Why is KRAS preferentially mutated in pancreatic cancer and why does this member of Ras have the highest overall mutagenic propensities relative to the other two, closely related Ras members, HRAS and NRAS?" (PMID 25265995, 2014). "Nonetheless, it is apparent that miR-29a modulates extracellular IGF-1/IGF-1R signaling in PSCs, and intracellular NRAS expression in pancreatic cancer cells, which indicates a functional role of the molecule in tumor-stromal crosstalk via insulin/IRF -RAS/MAPK signaling mechanism in PDAC." (PMID 32660466, 2020). "Once again, with more than 94% Pancreatic cancer patients carrying KRAS mutation and RAS genes (KRAS, NRAS, and HRAS) were observed to interact with each other through their mutations status and gene expression, it is highly expected that RAS genes could be highly associated with survival outcome." (PMID 30517129, 2018). "Mutant KRAS–SOS1–WT RAS allosteric signaling promotes growth of KRAS-mutated pancreatic cancer cell xenografts, but has not been assessed for mutant HRAS- or NRAS-dependent transformation." (PMID 33924994, 2021).
uveal melanoma (39 papers, 1991 to 2026). A melanoma derived from melanocytes of the uveal tract. "Mutations in BRAF, KIT and NRAS are rarely seen in uveal melanoma; however more than 80 percent of uveal melanomas have mutations in GNAQ or GNA11." (PMID 26334521, 2015). "Responses were seen in tumours harbouring BRAF fusions, GNA11, GNAQ, KRAS, NF1, and NRAS alterations, most frequently in low-grade serous ovarian cancer, central nervous system tumours, and uveal melanoma." (PMID 41664938, 2026). "Genomic patterns of BAP1mut non-uveal melanomas differed substantially from those of uveal origin in terms of mutational load and driver oncogenes: NF1, BRAF, and NRAS mutations were frequent, often with numerous co-mutations." (PMID 38903495, 2024). "Mutation analysis of tumor tissue revealed BRAF V600E/K mutation in 16 (64%), NRAS mutation in 2 (8%) and GNAQ or GNA11 mutation in 4 (n = 2, 8%; uveal melanoma; n = 2, 8%, primary CNS melanoma) patients." (PMID 36997799, 2023). "In CMs, uveal melanoma-related hotspot mutations appear to often co-occur with the mutations affecting the CM driver genes such as BRAF, NRAS, KIT, NF1, and ATRX." (PMID 37761808, 2023). "Genes that were known to be mutated in cutaneous and uveal melanoma subtypes, including BRAF, NRAS, NF1, GNAQ and GNA11, were rarely mutated in our cohort of patients." (PMID 30847022, 2019). "Mutations were found in 10 of the 19 uveal melanomas, with equal numbers of GNA11 and GNAQ mutations, but there were also two NRAS mutations." (PMID 28228113, 2017). "Uveal melanomas, in contrast to conjunctival melanomas, lack BRAF or NRAS mutations but frequently have mutations in GNAQ, GNA11, BAP1, SF3B1 or EIF1AX." (PMID 28938534, 2017). "We thus screened for activating mutations in the NRAS, HRAS, KRAS and BRAF genes in uveal melanoma cell lines and primary uveal melanomas." (PMID 15928660, 2005). "We identified BRAF mutations in 21/74 (28%) patients, NRAS mutations in 4/74 (5.4%) patients, NF1 mutations in 1/74 (1.4%) patients and GNAQ mutations in 1/74 (uveal melanoma) (1.4%) patients, as well as BRAF/NRAS (1/74; 1.4%) and GNAQ/NF1 (1/74; 1.4%) double mutations." (PMID 32785074, 2020). "No BRAF, NRAS or NF1 mutations were detected in uveal melanoma samples." (PMID 38903495, 2024). "We also detected nucleotide transitions resulting in gene activation in NRAS (Q61K, Q61R), in the promoter region of TERT (chr5:1295250 G > A), and in GNA11 (R183C), the latter being frequent in uveal melanoma and primary meningeal melanocytic tumors." (PMID 33578810, 2021). "However, it has been reported that mutations in BRAF and NRAS are absent in uveal melanoma." (PMID 35693877, 2019). "Mutations in mucosal melanoma are less common than in cutaneous or uveal melanomas and occur in descending order of frequency as: CKIT (20%), NRAS (5%) or BRAF (3%)." (PMID 25030020, 2014). "GNAQ and GNA11 mutations were common in uveal melanomas, while MAP-Kinase mutations were frequent in non-uveal melanomas with NF1, BRAF V600 and NRAS Q61 mutations occurring in decreasing frequency, consistent with a strong UV association." (PMID 38903495, 2024). "Interestingly, the downstream effectors of BRAF and NRAS, MEK, ERK and ELK, were constitutively activated in uveal melanomas." (PMID 25280020, 2014). "Although many uveal melanoma samples have been studied for BRAF and NRAS mutations, few have been analysed for MAPK activation and there is the implicit assumption that this pathway is not involved in uveal melanoma genesis." (PMID 15928660, 2005). "Interestingly, activation of the MAPK and PI3K survival pathways is observed in uveal melanoma; however, driver mutations in BRAF or NRAS commonly present in cutaneous melanoma are not observed in uveal melanoma." (PMID 34533562, 2021). "In contrast, uveal melanomas did not exhibit mutations in BRAF and NRAS." (PMID 25280020, 2014).
uveal melanoma (continued). "Mutations of NRAS, KRAS, and HRAS occur in 10–25%, 2%, and 1% of non-uveal melanoma, respectively, including those arising both on sun-exposed and sun-unexposed skin, mucosal, and acral melanomas; in contrast, RAS mutations are rarely observed in uveal melanomas." (PMID 30934534, 2019).